INS (insulin)
Diseases named in the same sentence as INS in open-access papers (continued):
Sharing a sentence is not in itself a finding about the gene and the disease.
insulinoma (continued). "Insulin secretion and peripherally detectable C-peptide levels in comparison with insulinoma are nonetheless lower." (PMID 37371827, 2023). "Normal insulin release index values are less than 0.3, but in insulinoma patients, this value can reach more than 0.4 or even more than 1.0." (PMID 36459334, 2023). "It plays a crucial role in the physiological process of regulating insulin secretion and is called a glucose sensor in insulinoma β-cells." (PMID 36851050, 2023). "In the present study, we analyzed insulin granule movement in an INS-1 insulinoma cell line, but physiologically, it would be critical to analyze higher-order samples, such as pancreatic islet cells." (PMID 38124716, 2023). "Conversely, overexpression of Rab26 inhibits insulin secretion in pancreatic insulinoma cells and freshly isolated mouse islets." (PMID 37289842, 2023). "In the majority of cases, insulinomas are benign and yet the symptoms (mainly hyperinsulinemic hypoglycemia due to secretion of insulin by the lesion) are severe and require fast and accurate treatment." (PMID 37242457, 2023). "Insulinoma, featured with abnormally secreting insulin contrary to the NFPNET, can repeatedly lead to severe hypoglycemic neuro-glycogenic and sympathetic overexcitement symptoms." (PMID 37772258, 2023). "It was previously reported that β cell-specific, Men1-deficient mice that lack exons 3–8 or exon 3 develop functional insulinomas with significantly elevated levels of serum insulin levels." (PMID 37679316, 2023). "A valid option to control hyperglycemic symptoms includes diazoxide, which is an inhibitor of insulin release that acts on ATP-sensitive potassium channels on insulinoma cells and is effective in approximately 50% of cases." (PMID 37103745, 2023). "Many of the animal pNEN cell lines are derived from early-stage insulinomas and were developed to create cell models for diabetes research, making stable long-term insulin-producing and responding lines." (PMID 37568572, 2023). "Insulinoma showed a major rate of hypermethylation among the other subgroups of functioning PanNENs, especially in epigenetic modifying enzymes as INS/IGF2 locus, CDNK1C, MEN1, KDM6A, MLL3/KMT2C, YY1, KDM5B, and SMARCC1." (PMID 36830839, 2023). "We therefore tested if the expression of affected genes was important for insulin secretion in a mouse insulinoma β-cells line." (PMID 37758822, 2023). "During surgical procedure, infusion of glucose is discontinued to monitor glucose level, in particular the insulin/glucose ratio, because it seems relevant in assessing successful removal of an insulinoma." (PMID 37103745, 2023). "There also exists another possibility that insulinoma secretes a large amount of insulin, which affects glucose metabolism and then lipid metabolism." (PMID 37033225, 2023). "In functional tumors, measurement of specific hormones is appropriate [glucagon in glucagonoma, vasoactive intestinal peptide (VIP) in VIPoma, gastrin in gastrinoma, insulin in insulinoma, etc.]." (PMID 36950054, 2023). "Two insulin-positive lymph node metastases were removed in a patient with two primary macro-insulinomas (1.8 and 2.0 cm)." (PMID 37894286, 2023). "Apelin-13 also inhibits insulin secretion stimulated by high glucose concentrations (10 mM) as well as glucagon-like peptide-1 (GLP-1)-enhanced insulin secretion in insulinoma cells." (PMID 37424869, 2023). "The insulin concentration level of insulinoma is generally less than 1000 mu/ml, and the increase in insulin concentration is synchronized with the increase in C-peptide levels, while the insulin concentration of IAS patients is often greater than 1000 mu/ml." (PMID 36844104, 2023). "The isolated compounds of L. sylvestris were screened on insulin-secreting rat insulinoma (INS-1E) cells to evaluate the insulin secretion at a concentration of 100 μg/mL." (PMID 37631052, 2023).
insulinoma (continued). "Amylin, an islet amyloid polypeptide, regulates insulin secretion/glucose homeostasis and is a crucial constituent of the amyloid in insulinomas." (PMID 36980580, 2023). "Insulinoma is a rare neuroendocrine tumor that overproduces insulin, resulting in hypoglycemic symptoms." (PMID 37292547, 2023). "MT1- and/or MT2-mediated melatonin action decreases glucose-stimulated insulin secretion in isolated rat pancreatic islets and rat insulinoma beta-cells." (PMID 36768693, 2023). "The knock-down of ATP4A in the insulinoma cell line MIN6 led to decreased glucose-stimulated insulin secretion." (PMID 37772258, 2023). "Insulinomas are the most common type of functioning pancreatic NETs, originating from the insulin-producing beta cells in the islets of Langerhans." (PMID 37242457, 2023). "Insulinomas are functional PNETs that arise from the pancreatic beta cells, resulting in unregulated secretion of insulin." (PMID 37046665, 2023). "GLP-1R is a G protein-coupled receptor that regulates insulin secretion and is an important target for diagnosis of insulinoma." (PMID 37455905, 2023). "The primary role of insulin is to regulate blood glucose levels, but in insulinomas, the hormone is secreted inappropriately and intermittently, causing episodic hypoglycemic symptoms." (PMID 37568540, 2023). "Additional laboratory studies for the diagnosis of insulinomas includes quantitation of insulin, glucose, C peptide, and proinsulin." (PMID 37046665, 2023). "Overexpression of hsa-miR-212-5p significantly enhances glucose-stimulated insulin secretion in rat insulinoma cells and restores insulin responsiveness." (PMID 38027164, 2023). "To overcome the limitation of using insulinoma cells to investigate the role of GIV in insulin secretion, we applied GIV shRNA downregulation to dissociated murine islet cells." (PMID 36822326, 2023). "At the end of fasting, an insulin concentration ≥ 5 μIU/mL and a proinsulin concentration > 22 pmol/L represent the cutoffs for the diagnosis of insulinoma." (PMID 37685358, 2023). "In fact, 10 mIU/L insulin level is considered a cutoff value in diagnosis of insulinoma in the face of glucose levels <3.5 mmol/L." (PMID 38260191, 2023). "Taken together, our results suggest that Rab26 serves as a negative regulator to restrict insulin secretion in pancreatic insulinoma cells and islets." (PMID 37289842, 2023). "Recently, the diagnosis of insulinoma mainly depends on clinical symptoms and the assessment of serum glucose, insulin, C-peptide, and β-hydroxybutyrate levels." (PMID 37772258, 2023). "Coeliac angiography and percutaneous transhepatic portal venous sampling have also been applied in the past to exclude (small) insulinomas and prove the excess secretion of insulin, respectively." (PMID 37371827, 2023). "Conversely, overexpression of Rab26 suppresses insulin secretion in both insulinoma cell lines and isolated mouse islets." (PMID 37289842, 2023). "By incubating insulin-producing insulinomas Min 6 cells with Ac4ManNAz for 3 days, the cells expressed azido groups on the cell membrane protein through the conversion of intracellular ManNAz into an azido sialic acid derivative." (PMID 37907476, 2023). "Our results showed that depletion of Rab26 promotes insulin secretion in mice or pancreatic insulinoma cells, while overexpression of Rab26 inhibits insulin secretion in both beta cell lines and freshly isolated islets." (PMID 37289842, 2023). "Although a 72-h starvation induction test is recommended as the biochemical golden standard to diagnose insulinoma, the most commonly used approach is opportune blood testing of plasma glucose, insulin, and C-peptide levels during hypoglycemic episodes." (PMID 36459334, 2023). "Biochemical detection of insulinoma by supervised 72-hour fasting test with plasma glucose, insulin, C-peptide, and proinsulin level measurements remains the gold standard of diagnosis." (PMID 36819415, 2023).
insulinoma (continued). "We have demonstrated that natural derivatives—leucettines can promote insulin secretion by insulinoma cells, hiPSC-derived beta islets, and isolated mouse pancreatic islets cultured in vitro." (PMID 37195917, 2023). "Insulinoma β-cells express glucose transporter-2 (Glut2), which can be used as a sensor molecule to regulate insulin secretion." (PMID 36851050, 2023). "The gold standard for diagnosing insulinomas is measuring insulin levels after a 72 h fasting test, which demonstrates close to 100% sensitivity and specificity." (PMID 37623030, 2023). "This study aimed to investigate the effects of perfluorooctanesulfonic acid (PFOS) exposure on glucose-stimulated insulin secretion (GSIS) of rat insulinoma (INS-1) cells and the potential protective effects of procyanidins (PC)." (PMID 36851050, 2023). "Glibenclamide (used to treat type 2 diabetes mellitus) promoted the release of NPY from hamster insulinoma tumor cells, and NPY blocked insulin release in the insulinoma RIN 5AH cell line; the latter action was due to the Y1R/adenylyl cyclase inhibition." (PMID 37373115, 2023). "Dogs can develop a tumour of the pancreas that produces too much insulin, which is called an ‘insulinoma’." (PMID 36288153, 2022). "Insulin-stimulated mouse insulinoma cell proliferation is dependent on both PI3K/AKT and RAF1/MAPK kinase pathways." (PMID 36232796, 2022). "In our own studies, we and others have shown that NFATs do indeed translocate to the nucleus in response to DYRK1A inhibitors, and also appear to play a central role in insulin gene expression in human insulinomas." (PMID 35700053, 2022). "This was suggested by data showing that several-fold overexpression of ApoM in WT mice improves glucose tolerance and that ApoM-containing lipoproteins can stimulate insulin secretion from a mouse insulinoma cell line." (PMID 35104242, 2022). "To investigate the impact of c.188-31G>A mutation associated with PNDM on mature beta-cells, we decided to overexpress wild type and mutant INS transcripts in the insulinoma MIN6 cell line." (PMID 35955956, 2022). "Hyperinsulinemic hypoglycemia remains a clinical challenge to be diagnosed, as well as a difficult pathology to distinguish from insulinoma or another insulin-producing tumor." (PMID 35296370, 2022). "The GIPR was firstly identified in transplantable insulinoma and insulin-secreting β cell line of hamster." (PMID 36860432, 2022). "In vitro, the treatment of human β-cells and human insulinomas with estrogens has been shown to enhance proliferation and insulin secretion." (PMID 35406570, 2022). "Potential insulinoma formation is unlikely based on the insulin secretion behavior and gene expression profile." (PMID 35769100, 2022). "Mixed clinical syndromes have not been described in dogs with endocrine pancreatic tumours, hence, insulinomas are named after insulin, its principal hormone, and its most common clinical sign: hyperinsulinaemia-induced hypoglycaemia." (PMID 36288153, 2022). "This response has been shown previously following end of chronic insulin administration in rats in our model and by others, and is a known response following removal of insulinomas in rats." (PMID 35982111, 2022). "Members of the AKT family are part of signaling cascades that positively regulate β cell mass and insulin secretion; however, AKT1 overexpression is associated with glucose tolerance and insulinoma formation." (PMID 35769100, 2022). "A similar model of diagnosing insulinoma includes fasting insulin, fasting C-peptide, 1-h C-peptide, and 2-h insulin concentrations." (PMID 35916979, 2022). "The same study reported cooperativity between MafA, PDX1, and E47/β2 toward INS activation in rat and mouse insulinoma cell lines." (PMID 36272648, 2022). "Considering that insulinoma patients release a large amount of insulin, the improvement of plasma glucose level after taking anhydrous glucose powder is still relatively slow." (PMID 35916979, 2022).
insulinoma (continued). "The cluster insulin secretion responses and endocrine and oncogene gene expression profiles were inconsistent with insulinoma characteristics." (PMID 35769100, 2022). "Altered splicing due to homozygous mutation led to the creation of two unstable mutant transcripts and results in failure of any translated INS product in insulinoma cells." (PMID 35955956, 2022). "Both adult human β cells and insulinoma cells secrete low amounts of insulin under basal conditions and not only after glucose or KCl challenge." (PMID 35378291, 2022). "Fifth, the information on insulin staining of samples after surgical resection was limited, whereas it would be more reliable in confirming the removal of insulinoma using insulin staining." (PMID 35698198, 2022). "Some negligible signal was detected in MIN6 mouse insulinoma cells due to possible cross-reactivity with human anti-insulin antibodies." (PMID 35955956, 2022). "In children, the gastrin-producing NENs (gastrinoma) and insulin-producing NENs (insulinoma) are the most common functional pancreatic NENs." (PMID 36291833, 2022). "For example, insulinoma, an insulin-producing tumor most commonly found in the pancreas, typically presents with hypoglycemic episodes." (PMID 36233409, 2022). "In contrast, BMI, 0-h C-peptide and 0-h insulin were significantly higher, and HbA1c, 0-h plasma glucose, 1-h and 2-h plasma glucose concentrations were significantly lower in the insulinoma than in the control group." (PMID 35916979, 2022). "This study examined the effect of collagen IV-β1-integrin on exocytotic proteins (Munc18-1, Snap25, and Vamp2) involved in insulin secretion using rat insulinoma (INS-1) cell line." (PMID 35573663, 2022). "On the contrary, in the case of auto‐ingestion of sulfonylureas that stimulate endogenous insulin secretion, insulin, proinsulin and C‐peptide levels are elevated mimicking thereby an insulinoma." (PMID 36117266, 2022). "A decrease in the oscillations of intracellular Ca2+, reducing the proteolysis of SNAP-25, and impairing insulin secretion was observed in RINm5F insulinoma cells treated with 1 μM of sodium arsenite for 72 h." (PMID 35651975, 2022). "In canine insulinomas, circulating insulin concentrations are generally within or above the reference interval (2–21 μU/mL)." (PMID 36288153, 2022). "Insulinoma β-cells are overproducers of insulin, so they promote hypoglycemia and, consequently, the development of symptoms of neuroglycopenia and the catecholaminergic response." (PMID 35406777, 2022). "Like dogs with insulinoma, humans with functional insulinomas demonstrate clinical signs of hypoglycaemia secondary to insulin hypersecretion, and surgical and medical treatment strategies are the same in both species." (PMID 36288153, 2022). "Mechanistic analyses have shown that 5-HEPE enhances glucose-dependent insulin secretion in mouse insulinoma cells and human intestinal carcinoma cells." (PMID 35054892, 2022). "SB increased insulin gene expression and β cell function in the islets of juvenile diabetic rats and the rat insulinoma β cell line RIN 1046-38." (PMID 35046383, 2022). "As detailed above, differentiated clusters exhibited some level of regulated insulin secretion while insulinomas tend to have exceedingly high, unregulated insulin secretion in response to all glucose concentrations, high or low." (PMID 35769100, 2022). "Over 95% of insulinomas can be diagnosed by serial plasma glucose and insulin levels during a 72 h fast showing hyperinsulinemic hypoglycemia." (PMID 36291833, 2022). "Insulinomas are a class of pancreatic tumors characterized by oversecretion of insulin and, consequently, hypoglycemia." (PMID 36272648, 2022). "Four patients in the hypercalcemia group developed insulin-producing liver metastases, and the remaining seven had new insulinomas." (PMID 35698198, 2022).
insulinoma (continued). "shRNA-mediated silencing of Ide in the INS1E insulinoma cell line (INS1E-shRNA-IDE cells) resulted in decreased insulin secretion in response to glucose." (PMID 35832432, 2022). "Our previous studies have demonstrated a crucial role for collagen IV-β1-integrin interactions in the promotion of insulin secretion, among other enhancements, from rat insulinoma line, INS-1 cells." (PMID 35573663, 2022). "Levels were significantly (p < 0.001 to p < 0.01) lower than expression in insulin-secreting mouse insulinoma MIN6 cells which were used as positive control." (PMID 36551163, 2022). "The concurrent occurrence of blood glucose that is below 3.5 mmol/L and plasma insulin that is above 10 μU/mL is characteristic of a canine insulinoma." (PMID 36288153, 2022). "The diagnosis of an insulinoma requires the demonstration of the simultaneous occurrence of low blood glucose levels and either normal or elevated blood insulin levels." (PMID 36288153, 2022). "Stimulation of endogenously expressed TRPM3 channels has been shown to trigger insulin secretion by insulinoma cells." (PMID 33603674, 2021). "As a mouse model of endogenous insulinoma, a mouse strain with rat insulin gene-2 promoter used to drive transgenic expression of simian virus 40 large T antigen (Rip-Tag2) was applied in a limited number of the previous studies." (PMID 34294854, 2021). "Suppression of AKT/PI3K pathway and induction of nuclear mTOR (Ser2481, Ser2448) expressions by melatonin sensitizes rat insulinoma INS-1E cells to insulin through increasing the expression of insulin receptor substrate." (PMID 33789681, 2021). "Other in vitro studies have revealed that apoA-I and apoA-II in both lipid-free and lipid-associated forms increase insulin synthesis and glucose stimulated insulin secretion (GSIS) in the MIN6 and Ins-1E pancreatic insulinoma β-cell lines." (PMID 33918571, 2021). "In conclusion, GDC-0449 was shown to effectively suppress both proliferation of MEN1 tumor beta cells in vivo and reduce insulin secretion by insulinomas, revealing itself to be a promising therapy against MEN1 insulin-secreting pNETs." (PMID 33919851, 2021). "The critical role of CCDC186 in cargo sorting and insulin secretion upon stimulation was recently confirmed in rat insulinoma cells." (PMID 33259146, 2021). "In agreement, disrupting Hnf4a expression in mouse islets or insulinoma cells resulted in impaired glucose-stimulated insulin secretion." (PMID 34732735, 2021). "Cafestol stimulated clonal rat insulinoma cell line (INS-1E) to secrete insulin and increase glucose uptake in muscle cells." (PMID 34832525, 2021). "Transfection of a small interfering RNA specific for Pdx1 in pancreatic islets insulinoma cell line shows that Pdx1 directly regulates the insulin transcription promotor." (PMID 34177802, 2021). "To understand the role of MICU2 in stimulus-secretion coupling in pancreatic β cells, we silenced MICU2 in INS-1 832/13 cells, a rodent-derived insulinoma cell line, and in EndoC-βH1 cells, a human embryonic insulin-secreting cell line." (PMID 33932586, 2021). "Insulinomas are rare insulin-secreting functional pancreatic neuroendocrine tumours, with an estimated incidence of 1–4 per million per year." (PMID 34374651, 2021). "The main limitation to insulinoma-derived cell lines is the varying insulin-secretory responses to glucose when compared to normal β cells." (PMID 34940547, 2021). "In this study, the synthetic cal14.2b (s-cal14.2b) from the unusual Californiconus californicus demonstrated bioactivity on NIT-1 insulinoma cell lines stimulating insulin secretion detecting by high performance liquid chromatography (HPLC)." (PMID 34440140, 2021). "We showed that butyrate protected beta cells from cytokine-induced impairment of GSIS and reduced insulin content in three different beta cell models; isolated mouse islets, human EndoC-βH1 beta cells and rat insulinoma INS-1E beta cells." (PMID 34638768, 2021).